JUN (Jun proto-oncogene, AP-1 transcription factor subunit)
Diseases named in the same sentence as JUN in open-access papers (continued):
Sharing a sentence is not in itself a finding about the gene and the disease.
asthma (14 papers, 2010 to 2026). "JUN activation appears to be implicated in airway inflammation by contributing to regulate the expression of Th2 cytokines, chemokines, growth factors, and adhesion molecules, which is associated with several inflammation related disorders such as asthma and allergy (Haeggström and Funk, 2011)." (PMID 33968984, 2021). "The expression of JUN is repressed in the early stage of cell trajectories for all three asthma patients." (PMID 41550933, 2025). "In Asthma 3, JUN is also repressed while the expression patterns of IL7R, IL32, and CCL5 are more similar to healthy controls." (PMID 41550933, 2025). "In Asthma 1 and Asthma 2, the expression dynamics of JUN, SPI1 and six inflammatory response related genes are almost the same." (PMID 41550933, 2025). "Another male-specific pQTL rs11207327 linked with CD5 levels also modulates the expression of genes (JUN, KRT79, TACSTD2), and it is associated with diseases and traits (Asthma, self-reported haemorrhoids and treatment with estriol product)." (PMID 38326779, 2024). "The results showed gradually elevated expression of p-NF-κB, p-c-FOS, and p-c-JUN from normal subjects to patients with mild/moderate asthma to patients with severe asthma (p < 0.01 severe asthma vs. normal; p < 0.05 severe asthma vs. mild/moderate asthma)." (PMID 32112175, 2020). "In our study, the expression of transcription factors, including phosphorylated NF-κB, c-FOS and c-JUN, was higher in patients with severe asthma than in those with mild/moderate asthma or in healthy controls." (PMID 32112175, 2020). "In Asthma 1 and Asthma 2, the repression of JUN seems to be replaced by the expression of SPI1." (PMID 41550933, 2025). "c-CBL/LCK/c-JUN/ETS1/CD28 axis was beneficial for asthma, and may provide novel targets for asthma therapy." (PMID 39342146, 2024). "In total, 6 genes were upregulated (e.g. CCL3L1, CCL4L2, GPR82) and 20 were downregulated (e.g. JUN, IFITM3, DUSP1, GNG7) in peripheral eosinophils of COPD patients compared to asthma." (PMID 39422548, 2024). "c-CBL alleviated asthma and suppressed Th2 differentiation by facilitating LCK ubiquitination, interrupting c-JUN activation and CD28 expression in vivo and in vitro." (PMID 39342146, 2024). "In this study, the IL-17 signaling pathway was found by the KEGG enrichment analysis to be an important pathway by which the PEF counteracted asthma, and 15 targets are involved (including the core targets MAPK1, MAPK14, MAPK3, and JUN)." (PMID 36172200, 2022). "It suggested that c-JUN and ETS1 may be involved in regulation of asthma development and Th2 differentiation by controlling CD28 expression, and LCK may function by control c-JUN/ETS1/CD28 axis." (PMID 39342146, 2024). "c-CBL/LCK/c-JUN/ETS1/CD28 axis was partially involved in childhood asthma, and may provide novel insights for clinical treatment for asthma." (PMID 39342146, 2024). "A total of 129 overlapping targets between the PEF and asthma were obtained by jvenn online tools, among which five targets might play important roles: MAPK14, JUN, STAT3, MAPK3, and MAPK1." (PMID 36172200, 2022). "Our subsequent molecular docking showed that each bioactive compounds (quercetin, wogonin, luteolin, naringenin, and kaempferol) of MGMD has favorable binding abilities with STAT3, PTGS2, JUN, VEGFA, EGFR, and ALOX5, further arguing the potential molecular mechanism of action of MGMD in asthma." (PMID 33968984, 2021).
cardiac hypertrophy (14 papers, 2013 to 2024). "FOS and JUN transcription factors are thought to be among the first set of genes to be expressed in the context of pathological cardiac hypertrophy, and EP300 has been associated with cardiomyocyte enlargement." (PMID 28797094, 2017). "Other results indicated that Sirt6 blocks IGF signaling by interacting with c-JUN, inhibition of c-JUN or IGF signaling retards cardiac hypertrophy of Sirt6-deficient mouse hearts, thus preventing cardiac hypertrophy from progressing into heart failure." (PMID 37497437, 2023).
periodontitis (14 papers, 2015 to 2026). An acute or chronic inflammatory process that affects the tissues that surround and support the teeth. "Remarkably, our findings from both in vitro and in vivo experiments uncovered a novel role of the JNK/JUN/ NCOA4 axis in regulating macrophage ferroptosis in chronic apical periodontitis." (PMID 39744165, 2025). "A deep learning-based autoencoder predicted FOS and JUN to be critical immunosuppression genes and mediate immune suppression in periodontitis." (PMID 36045361, 2022). "Furthermore, this study initially verified that blocking JNK/ JUN/NCOA4 axis can effectively suppress macrophages ferroptosis, resulting in a decrease in the inflammatory status associated with chronic apical periodontitis." (PMID 39744165, 2025). "Moreover, the Healthy group showed higher nuclear JUN expression in the basal and suprabasal layers and connective tissue compared to the Periodontitis group." (PMID 41124422, 2025). "We conclude that UBC, JUN, and MMP14 are likely an optimal candidate group of host-derived biomarkers, in combination with oral pathogenic bacteria-derived proteins, for detecting periodontitis at its early phase by using salivary samples from patients." (PMID 26793622, 2015). "On the basis of our findings, we propose the cumulative use of UBC, JUN, and MMP14, possibly in combination with oral pathogenic bacteria-derived proteins, as putative biomarkers for early detection of periodontitis to be tested either at the RNA or protein level in salivary samples." (PMID 26793622, 2015). "Through the establishment of the in vitro and in vivo models, we have discovered that there is a direct correlation between the JNK/JUN/NCOA4 axis and the presence of macrophage ferroptosis during chronic apical periodontitis progression." (PMID 39744165, 2025). "In the IL-17 Signaling pathway, identified as the most suppressed CP, FOS, JUN, Matrix Metallopeptidase 13 (MMP-13), and C-C Motif Chemokine Ligand 20 (CCL20) were downregulated in periodontitis tissues (Log2FC<-1.5)." (PMID 41124422, 2025). "Recent studies utilizing single-cell sequencing (scRNA) technology in the periodontal tissues of periodontitis-affected or healthy individuals revealed the differential expression of the BCL6, FOS, and JUN MRs during osteoclastogenesis." (PMID 37834287, 2023). "JUN, FOS, KLF2, THBS1 and WIF1 were identified as key regulator in periodontitis and validated to be highly expressed in IPT through RT-qPCR." (PMID 36045361, 2022). "Five mRNAs, i,e., FOS, JUN, KLF2, WIF1, and THBS1, for further validation via RT-qPCR on 15 periodontitis and 15 healthy gingivae samples." (PMID 36045361, 2022). "The analysis of the transcriptomic datasets of human periodontitis (GSE16134 and GSE10334) and the immunosuppression genes by deep learning-based autoencoder techniques suggested that FOS and JUN were downregulated transcription factors with possible roles in periodontitis." (PMID 38241313, 2024). "In addition, during periodontitis, increased expression levels of the FOS and JUN genes were observed in CD4+ T-cells, indicating their importance in cell activation." (PMID 37834287, 2023). "Of the top 10 hub TFs, six “leader” immunosuppressive TF-target DEGs with plausible literature evidence were identified as key to periodontitis pathogenesis and included the down-regulated TFs (NFKB1, FOS, and JUN), as well as up-regulated TFs (HIF1A, STAT5B, and STAT4)." (PMID 33777111, 2021). "Importantly, ATF3, FOS, and JUN, that function in Tumor Microenvironment and PI3K Signaling in B Lymphocytes pathways, were exclusively downregulated in periodontitis in the non-diabetic patients." (PMID 38241313, 2024).
depression (13 papers, 2017 to 2026). "Dysregulation of this pathway, particularly involving key nodes like BDNF, RAF1, and downstream effectors such as JUN, has been increasingly implicated in the pathophysiology of Major Depressive Disorder." (PMID 41438694, 2026). "Notably, this is the first data demonstrating the mRNA levels of PPAR-γ, FOS, and JUN and their association with clinical response in depression population." (PMID 41479556, 2026). "The pro-inflammatory transcription factor JUN, which was markedly elevated in depression models, was dose-dependently attenuated by curcumin treatment, with high-dose administration exhibiting significantly greater efficacy than low-dose." (PMID 41438694, 2026). "In differential regulation analysis (DRA) to compare the transcriptomic profiles of peripheral blood lymphocytes from patients with MDD and subsyndromal symptomatic depression, JUN was found to be one of differentially regulated genes." (PMID 41479556, 2026). "EA treatment reduced the expression of c-JUN and c-JUN terminal kinase (JNK) in the hippocampus of CUMS depression model rats, suggesting that EA alleviates depression by regulating the MAPK/JNK signaling pathway." (PMID 39367470, 2024). "In PPIN, the main hubs such as AKT1, JUN, MAPK8 and STAT3 have already been reported to be involved in depression." (PMID 28954415, 2017). "Specifically, we observed that CUMS-induced depression models exhibited profound molecular dysregulation characterized by significant BDNF suppression, pathological EGFR overexpression, ERK2 downregulation, pro-inflammatory JUN elevation, RAF1 repression, and chronic stress-driven TNF upregulation." (PMID 41438694, 2026). "Kaempferol and quercetin had been reported to relieve symptoms of depression and exhibited antidepression effects through acting on interleukin-6 (IL6), mitogen-activated protein kinase 1 (MAPK1), signal transducer, and activator of transcription 3 (STAT3) and transcription factor AP-1 (JUN)." (PMID 36045654, 2022).
glaucoma (13 papers, 2009 to 2025). Increased pressure in the eyeball due to obstruction of the outflow of aqueous humor. "In conclusion, we demonstrate MKK4/7 controlled RGC soma loss after glaucoma-relevant injury—possibly via somal DDIT3/JUN activation." (PMID 41397991, 2025). "JUN was shown to be important in RGC death after glaucoma-relevant insult, and EDN exposure caused JUN upregulation in cultured primary RGCs33." (PMID 32980857, 2020). "Additionally, ET-1 causes neuronal cell death in glaucoma by activating pro-apoptotic transcription factor JUN (the canonical target of JNK signaling)." (PMID 35269741, 2022). "Recently, the transcription factors JUN and DNA-damage inducible transcript 3 (DDIT3, also known as CHOP) were identified as critical regulators of RGC somal loss after glaucoma-relevant injury." (PMID 41397991, 2025). "Caspase 3 activation in RGCs and later RGC loss after EDN1 exposure was dependent upon JUN activation, similar to RGC death after glaucoma-relevant injuries including optic nerve crush and ocular hypertension." (PMID 35429992, 2022). "MAPK-JNK signaling and its canonical target JUN regulated RGC death after glaucoma-relevant insults such as axonal injury and chronic ocular hypertension." (PMID 32980857, 2020). "Previously, JUN has been shown to be an important pro-apoptotic signaling pathway after glaucoma-relevant axon injury." (PMID 28969695, 2017). "To determine whether Jnk2 and Jnk3 are required for JUN phosphorylation and RGC death in glaucoma, we assessed pJUN immunoreactivity and RGC soma loss in D2.Jnk2−/−Jnk3−/− mice." (PMID 29899326, 2018). "JUN was expressed in RGCs in a spatial and temporal pattern consistent with a role in RGC death after ocular hypertensive injury, an important risk factor for glaucoma." (PMID 28726785, 2017). "Furthermore, identifying the upstream activators of MKK4/7 in the context of glaucoma-relevant injury and elucidating the DDIT3/JUN-independent downstream effectors of MKK4/7 driving loss of somal viability and axonal degeneration will be important next lines of investigation." (PMID 41397991, 2025). "Therefore, MKK4/7 signaling may be a critical early mechanism governing RGC somal death via DDIT3/JUN activation and may also regulate axonal degeneration after glaucoma-relevant injury." (PMID 41397991, 2025). "Specifically, we examined the dual role of DDIT3 and JUN and their upstream regulators MKK4/7 in controlling RGC death after glaucoma-relevant injury." (PMID 41397991, 2025). "Here, we assessed the importance of DDIT3 and JUN, along with their upstream activators MKK4 and MKK7, in RGC degeneration after glaucoma-relevant injury." (PMID 41397991, 2025). "Previous studies demonstrated that JUN and DDIT3 were important regulators of RGC death after glaucoma-relevant injures." (PMID 32980857, 2020). "Considering EDN insult caused activation of JUN in 30% of RGCs and 69% of cCASP3+ RGCs were also JUN+ after EDN1 insult, it remained possible that JUN regulates EDN1-induced RGC death, similar to glaucoma-relevant RGC death." (PMID 32980857, 2020). "Future work should focus on the roles of both JUN and DDIT3 together in perpetuating glaucomatous RGC death and should elucidate upstream regulators of both JUN and DDIT3 after glaucoma-relevant injury." (PMID 31632741, 2019). "To further examine JNK signaling in glaucoma, we determined if JNK and JUN were phosphorylated in the retina using immunohistochemistry (pJNK and pJUN, respectively, phosphorylation induces an activated state)." (PMID 29899326, 2018). "Therefore, it is possible that JUN and/or DDIT3 are RGC-intrinsic regulators of EDN-induced RGC death, similar to after glaucoma-relevant injuries." (PMID 32980857, 2020). "Regardless of whether the inciting injury in glaucomatous neurodegeneration is extrinsic or intrinsic to RGCs, sequentially stepping upstream of JUN and DDIT3 activation may define the earliest events in glaucoma." (PMID 28969695, 2017).
glaucoma (continued). "It is further shown that JUN, a pro-death component of the JNK pathway in RGCs, can be activated in glaucoma in the absence of JNK2 and JNK3." (PMID 29899326, 2018).
rheumatoid arthritis (13 papers, 2013 to 2023). A chronic, systemic autoimmune disorder characterized by inflammation in the synovial membranes and articular surfaces. "JUN regulates the clinical course of rheumatoid arthritis by modulating the expression of pro-inflammatory cytokines and chemokines and inducing elevated Fre-1 expression and Fra-1 protein in peripheral blood in synovial macrophages." (PMID 36923645, 2023). "Among PSA T and NK cells, we also observed a downregulation of AP-1 transcription factors (JUN, JUNB, JUND, FOS) and regulators of activation (TNFAIP3, DUSP1) along with the upregulation of S100A11, a calcium-binding protein associated with rheumatoid arthritis." (PMID 35309349, 2022). "This study aimed to further investigate the correlation between three effective biomarkers (JUN, SOCS3, CXCL8) and immune infiltrating cells, which play a crucial role in rheumatoid arthritis (RA), specifically in RF-negative pJIA and oJIA." (PMID 38001449, 2023).
Sepsis (13 papers, 2016 to 2025). Sepsis is defined as life-threatening organ dysfunction caused by a dysregulated host response to infection. "In particular, JUN can directly activate sepsis-related genes, altering biological mechanisms associated with essential sepsis functional genes." (PMID 37510271, 2023). "Notably, Mmp3, a gene involved in the regulation of cardiac remodeling, can be directly regulated by JUN for both sepsis induction methods." (PMID 37510271, 2023). "Our analysis revealed that both JUN and EP300 play crucial roles in the two sepsis induction models." (PMID 37510271, 2023). "Among the sustained upregulated genes in neutrophils post sepsis, we identified ANXA1, MMP9, SIPR1, and JUN as the candidate genes." (PMID 33761636, 2021). "Likewise, when focusing on TFs related to the regulation of cytotoxicity genes (TBX21, EOMES, JUN, and RUNX3), alterations are evident within the sepsis cells." (PMID 41208955, 2025). "In sepsis, RELA, CEBPB, NFKBIA, STAT6, IRF8 and SPI1 were downregulated, with no significant change in NFKB1, JUN and GLI1." (PMID 39444551, 2024).
osteoarthritis (12 papers, 2013 to 2025). A noninflammatory degenerative joint disease occurring chiefly in older persons, characterized by degeneration of the articular cartilage, hypertrophy of bone at the margins and changes in the synovial membrane. "Meniscus models derived from female donors exhibited heightened cell proliferation activities, with the JUN protein involved in several potentially osteoarthritis-related signaling pathways." (PMID 38907358, 2024). "Four genes, MYC, JUN, DUSP1 and NFKBIA, were selected as potential diagnostic biomarkers in osteoarthritis." (PMID 36681837, 2023). "The results indicated that MCL1, JUN, and GADD45B exhibited relatively high AUC values, highlighting their significant classification ability and potential as biomarkers for osteoarthritis." (PMID 40826778, 2025). "LASSO regression and the Boruta algorithm validated the significant predictive ability of genes such as MCL1, JUN, and GADD45B, with their high AUC values indicating potential as osteoarthritis biomarkers." (PMID 40826778, 2025). "Consistently, we found that expression of MYC, JUN and DUSP1 was markedly reduced in synovial tissues of osteoarthritis patients than that of normal controls (p value < 0.05)." (PMID 36681837, 2023). "The verification result showed that the expression levels of IL6, VEGFA, JUN, IL-1β, and ATF3 were significantly increased in osteoarthritis samples (p < 0.05)." (PMID 30186872, 2018). "Among them, four genes (MYC, JUN, DUSP1 and NFKBIA) specifically expressed in immune system were identified and clinical samples revealed consistent change of these four genes in synovial tissue retrieved from patients with osteoarthritis." (PMID 36681837, 2023). "Finally, four feature genes, including MYC, JUN, DUSP1 and NFKBIA were identified, which had well predictive performance in osteoarthritis." (PMID 36681837, 2023). "JUN has been reported to stimulate the apoptosis of chondrocytes by increasing the level of PUMA (a pro-apoptotic factor) and BIM, serving an important role in osteoarthritis." (PMID 36681837, 2023). "MYC, JUN, DUSP1 and NFKBIA might be biomarkers and potential therapeutic targets in osteoarthritis." (PMID 36681837, 2023).
Arthritis (11 papers, 2005 to 2024). Inflammation of a joint. "Moreover, c-JUN has been reported as a key subunit of the AP-1 transcription factor which is involved in NF-κB activation and arthritis development." (PMID 32290250, 2020).